VHL (von Hippel-Lindau tumor suppressor)
Diseases named in the same sentence as VHL in open-access papers (continued):
Sharing a sentence is not in itself a finding about the gene and the disease.
Hereditary breast cancer (1 paper, 2014). Breast carcinoma that has developed in relatives of patients with history of breast carcinoma. "In conclusion, our study suggests that a deletion of the VHL and FANCD2 gene may be associated with coexistence of VHL disease and hereditary breast cancer, but further studies are needed in this regard." (PMID 25093046, 2014).
intrahepatic cholangiocarcinoma (1 paper, 2024). A carcinoma that arises from the intrahepatic bile duct epithelium in any site of the intrahepatic biliary tree. "In RCC, FTO promotes angiogenesis by inhibiting von Hippel-Lindau tumor suppressor (VHL) expression, whereas in intrahepatic cholangiocarcinoma (ICC), FTO suppresses angiogenesis by inducing TEA domain transcription factor 2 (TEAD2) expression." (PMID 39098905, 2024).
Leigh syndrome (1 paper, 2016). A progressive neurological disease defined by specific neuropathological features associating brainstem and basal ganglia lesions. "Indeed, a recent genome-wide screen identifies hypoxia and VHL inhibition as a potential therapy for mitochondrial diseases presenting with Leigh syndrome." (PMID 27923773, 2016).
leiomyoma (1 paper, 2013). A well-circumscribed benign smooth muscle neoplasm characterized by the presence of spindle cells with cigar-shaped nuclei, interlacing fascicles, and a whorled pattern. "Because most of the research involving VHL focuses on its loss of function and consequent cancer development, finding VHL up-regulated in growing leiomyoma appeared counterintuitive." (PMID 23785396, 2013). "VHL protein (pVHL) also plays an important role in microtubule stabilization and growth promoting rescue events, reflected in the network associations in leiomyoma from older black women." (PMID 23785396, 2013).
marginal zone lymphoma (1 paper, 2024). A usually indolent mature B-cell lymphoma, arising from the marginal zone of lymphoid tissues. "CGP additionally resulted in genetic counseling consultation for three patients: one patient with CLL who was found to have a BRCA2 mutation, one patient with CLL who was found to have an MSH6 mutation, and one patient with marginal zone lymphoma who was found to have a VHL mutation." (PMID 39449302, 2024).
Meniere disease (1 paper, 2025). A disease of the inner ear (labyrinth) that is characterized by fluctuating sensorineural hearing loss; tinnitus; episodic vertigo; and aural fullness. "The frequent misdiagnosis of ELST-related otologic symptoms such as Meniere’s disease underscores the importance of considering ELST in differential diagnoses, particularly in young patients with apparent “Meniere” symptoms and VHL risk factors." (PMID 41294695, 2025).
metabolic syndrome (1 paper, 2020). A cluster of metabolic risk factors for CARDIOVASCULAR DISEASES and TYPE 2 DIABETES MELLITUS. "Perhaps this is because the protein produced by missense germline alterations can maintain intrinsic function in the context of neoplasias and metabolic syndromes, including VHL." (PMID 33110457, 2020).
multiple sclerosis (1 paper, 2022). A progressive autoimmune disorder affecting the central nervous system resulting in demyelination. "In this report, we present for the first time a case of superimposed multiple sclerosis in both a mother and daughter with VHLD and highlight the possible connection between the VHL signaling pathway and multiple sclerosis pathophysiology as an exciting area for further study." (PMID 35260109, 2022).
nephrolithiasis (1 paper, 2023). The presence of a calculus in the pelvis of the kidney; this is most often composed of mineral salts and proteins. "Above all, our data demonstrate that loss of VHL promotes host inflammatory response and exacerbates nephrolithiasis." (PMID 37833251, 2023). "Utilizing Vhl+/mu mouse model, depletion of VHL exacerbated kidney inflammatory injury during nephrolithiasis." (PMID 37833251, 2023). "In order to comprehensively analyze the biological role of VHL during nephrolithiasis, we thus committed our ensued experiments with low concentration of GA (45 mg/kg)." (PMID 37833251, 2023). "To investigate the role of VHL in progression of nephrolithiasis, we used the Vhl mutant mice with heterozygous missense mutation (I117F, conserved with the I151F mutation in human, COSMIC ID: COSM17978)." (PMID 37833251, 2023). "Our data thus indicate that VHL protects kidney from inflammatory lesion induced by nephrolithiasis in a HIF -independent manner." (PMID 37833251, 2023). "However, it is unclear whether, and how, VHL is involved in nephrolithiasis-induced kidney injury and its related inflammatory process." (PMID 37833251, 2023).
oesophageal cancer (1 paper, 2008). "In oesophageal cancer, it is known that p16, FHIT and VHL are inactivated by promoter hypermethylation." (PMID 18219292, 2008).
oral squamous cell carcinoma (1 paper, 2023). "In addition to HIFα, VHL also inhibits NF-κB signaling by mediating K63-ubiquitination of IKKβ, and our previous study have verified that elevated VHL could inactivate β-catenin pathway, and impair the capacities of proliferation and invasion in oral squamous cell carcinoma." (PMID 36813772, 2023).
pancreatic cystadenoma (1 paper, 2013). A non-metastasizing cystic epithelial neoplasm arising from the exocrine pancreas. "Data suggest that VHL loss through LOH of chromosome 3p might be a common mechanism initiating cystogenesis in sporadic pancreatic cystadenomas." (PMID 23384121, 2013). "This further supports that VHL loss initiates cystogenesis in pancreatic cystadenomas." (PMID 23384121, 2013).
pancreatic disease (1 paper, 2009). "The novel model systems reported here will provide the basis for further functional and genetic studies to define molecular mechanisms involved in VHL-associated pancreatic diseases." (PMID 19340311, 2009). "The novel model systems reported here will provide the basis for further genetic studies to define molecular events involved in VHL-associated pancreatic diseases." (PMID 19340311, 2009). "Identification of these modifier genes and further comparative functional analysis utilizing mice deficient in Hif1α and Hif2α will provide insight into the precise molecular mechanisms leading to the development of VHL-associated pancreatic disease." (PMID 19340311, 2009). "Most significantly, we presented the first mouse model of VHL-associated pancreatic disease in mice lacking pVHL utilizing Pdx1-Cre transgenic mice to inactivate Vhl in pancreatic progenitor cells." (PMID 19340311, 2009).
parathyroid disease (1 paper, 2022). "Using NGS, we identified three pathogenic variants in two genes (CDC73 and MEN1), 10 likely pathogenic variants in six genes (CASR, CDC73, LRP5, MEN1, SDHA, and VHL), and 39 non-synonymous VUS variants that could be related to parathyroid disease." (PMID 35586626, 2022).
prostatic intraepithelial neoplasia (1 paper, 2024). "EAF2 and VHL double deficiency (EAF2−/−VHL+/−) mice exhibited increased vascular density compared to the control groups (wild-type, EAF2−/− and VHL+/−mice), thus resulting in a higher incidence of prostatic intraepithelial neoplasia and stromal inflammation." (PMID 39588149, 2024).
pulmonary oedema (1 paper, 2020). "We have generated a conditional deletion in mice of the von Hippel‐Lindau factor (VHL) in myeloid cells to determine the effect of a deregulated hypoxic response in pulmonary oedema." (PMID 32129933, 2020). "The deletion of VHL in pulmonary myeloid cells gave rise to pulmonary oedema, increased pulmonary vascular permeability and reduced performance during exertion." (PMID 32129933, 2020). "Our results demonstrate that deleting myeloid VHL results in pulmonary oedema, increased endothelial cell fenestration and an at least partially VEGF‐A‐independent increase in pulmonary permeability." (PMID 32129933, 2020).
rectal cancer (1 paper, 2025). A primary or metastatic malignant neoplasm that affects the rectum. "Here, we demonstrated clinical and prognostic values of VHL expression in rectal cancer (RC)." (PMID 40005423, 2025). "Our preliminary study indicated that VHL expression may have prognostic significance in rectal cancer (RC)." (PMID 40005423, 2025).
renal failure (1 paper, 2019). "Renal tumor involvement and thus the risk for renal failure is not uncommon in VHL, and increases the risk for nephrogenic systemic sclerosis if using Gd contrast." (PMID 31384339, 2019).
retinal degeneration (1 paper, 2024). Degeneration of the retina. "Unexpectedly, however, the conditional knock-out mice targeting the VHL-HIF-VEGF pathway showed not only retinal degeneration but also drusen-like deposits." (PMID 38731137, 2024). "However, of interest, our conditional knock-out mice targeting the Von Hippel Lindau (VHL)-HIF-VEGF pathway showed not only retinal degeneration but also drusen-like deposits." (PMID 38731137, 2024).
Retinal dystrophy (1 paper, 2025). Retinal dystrophy is an abnormality of the retina associated with a hereditary process. "We are not aware of any previous co-occurrence of VHL and retinal dystrophy." (PMID 40826436, 2025).
retinitis pigmentosa (1 paper, 2025). Retinitis pigmentosa (RP) is an inherited retinal dystrophy leading to progressive loss of the photoreceptors and retinal pigment epithelium and resulting in blindness usually after several decades. "While ablating VHL provides therapeutic effects in a mouse model of retinitis pigmentosa, upregulation of HIFs may also promote neovascularization in response to elevated vascular endothelial growth factors (VEGFs) induced by HIFs." (PMID 39932789, 2025). "The rescue of photoreceptors by rod-specific VHL ablation may be due partially to this photoreceptor-RPE crosstalk positively contributing to a strategy for treating retinitis pigmentosa." (PMID 39932789, 2025).
rhabdomyolysis (1 paper, 2022). Necrosis or disintegration of skeletal muscle often followed by myoglobinuria. "It has been found that VHL deletion (and increased HIF1-α activity) in tubular cells can provide protection against AKI due to IRI and rhabdomyolysis." (PMID 36139884, 2022).
Splenomegaly (1 paper, 2011). Abnormal increased size of the spleen. "Indeed, macroscopic examination of tamoxifen-treated Vhlfloxed-UBC-Cre-ERT2 mice revealed marked splenomegaly, an indicator of increased activity of the oxygen-VHL/PHD/HIF sensing pathway, as seen in Phd2 deficient and Phd1:Phd3 double knock-out mice." (PMID 21811636, 2011).
thyroid cancer (1 paper, 2014). "Expression of VHL in thyroid cancers and its association with clinicopathological parameters." (PMID 25490036, 2014). "Since the results revealed the absence of common genetic or epigenetic modifications responsible for VHL gene downregulation, further analysis including a more detailed understanding of gene regulation and VHL interactions, is required to elucidate the mechanism of VHL effect in thyroid cancer." (PMID 25490036, 2014). "Only one research paper has analyzed the methylation status of VHL in patients with thyroid cancer." (PMID 25490036, 2014).
uveal melanoma (1 paper, 2025). A melanoma derived from melanocytes of the uveal tract. "Knowing this and as we have presented, uveal melanoma patients with monosomy of chromosome 3p (implicating VHL and BAP1) and gain of chromosome 8q (PTK2) have a worse prognosis." (PMID 40000790, 2025). "However, the relationship between chromosome 3 loss and the subsequent loss of VHL in uveal melanoma patients has not yet been explored." (PMID 40000790, 2025). "However, the implications of VHL in uveal melanoma patients have yet to be explored." (PMID 40000790, 2025).
tumor (1,412 papers, 1994 to 2026). "VHL mutations show highly vascularized tumor across various organs due to HIF activation and upregulation of HIF-target genes such as VEGF in non-endothelial cells (ECs), influencing neighboring ECs and triggering abnormal angiogenesis." (PMID 42003386, 2026). "We used 8 ccRCC PDX lines representing a range of RCC sites (primary tumor and metastases), histologic features (tumor grade, sarcomatoid/rhabdoid features), and VHL mutation status." (PMID 41480764, 2026). "To further validate SKIDA1 as a clinically relevant target in ccRCC, we performed immunoblot analysis of additional ccRCC tumor and patient-matched normal samples, genotyped to confirm VHL mutation in all tumor samples." (PMID 40240354, 2025). "The loss of VHL gene expression, which can occur through mutations, deletions, or silencing, is a hallmark of certain cancers and can lead to more aggressive tumor behavior and a worse prognosis." (PMID 40005423, 2025). "In conclusion, our study involving 357 patients demonstrated that safe complete resection is crucial for achieving superior long-term local tumor control in both sporadic and VHL-associated sHBs." (PMID 39950840, 2025). "Although pRb is best known as a tumor suppressor, in this study, we describe a context-specific potential for this protein to act as an oncogene when dysregulated by VHL loss." (PMID 40240354, 2025). "In a phase II trial, belzutifan demonstrated a 60% reduction in tumor size and a 70% improvement in progression-free survival in patients with VHL-associated RCC." (PMID 40937003, 2025). "The syndrome is caused by germline mutations in the VHL tumor suppressor gene, located on chromosome 3p25.3, which plays a critical role in cellular oxygen sensing and tumor suppression." (PMID 40937003, 2025). "By utilizing unique tumor spheroid models of RCC to better recapitulate a 3D growing tumor, we demonstrate that VHL-mutated tumors are less infiltrated by NK cells compared with VHL-restored tumors." (PMID 40736709, 2025). "The von Hippel–Lindau (VHL) tumor-suppressor gene, which is mutated in nearly 90% of advanced ccRCC cases, encodes a critical component of an E3-ubiquitin-ligase complex responsible for the oxygen-dependent degradation of HIF-α subunits." (PMID 41451091, 2025). "This is the first study to demonstrate FSH-receptor expression by cells of VHL-associated tumors, with distinct expression patterns in different tumor types." (PMID 41024941, 2025). "Various natural mutations with inactivation of the VHL gene, a tumor suppressor gene, have been reported in most cases of hereditary von Hippel-Lindau disease and sporadic clear cell renal cell carcinomas (ccRCCs)." (PMID 40906297, 2025). "Cluster 1 comprises, amongst others, pathogenic variations in the SDHX and VHL genes, which result in tumour development through the stimulation of the HIF1α-signaling pathway." (PMID 41276740, 2025). "In ccRCC, loss of function of the VHL/HIF pathway leads tumor cells to sustain elevated glycolysis under hypoxic conditions, similar to the Warburg effect." (PMID 41555916, 2025). "For subgroup analysis by genetic mutations, the CDX model with BAP1 mutations exhibited the most rapid tumor growth rate, compared with the models with VHL, PBRM1, and SETD2 mutations (P < 0.01)." (PMID 40856833, 2025). "In contrast, tumor proteomes demonstrated canonical hallmarks associated with VHL loss, including elevated glycolysis and hypoxia-associated proteins, suppressed aerobic metabolic pathways, and altered fatty acid metabolism." (PMID 40753869, 2025). "A noteworthy example is observed in individuals with VHL syndrome, a hereditary disease characterized by a heterozygous germline loss-of-function mutation in the VHL tumor suppressor gene." (PMID 39470609, 2025). "Over 1000 distinct VHL mutations have been identified, with genotype-phenotype correlations influencing disease severity and tumor types." (PMID 40937003, 2025).
tumor (continued). "An independent study assessed the efficacy of three models in forecasting tumor mutation burden and the status of VHL mutations." (PMID 40217721, 2025). "The loss or reduced expression of the VHL gene is common and is directly correlated with increased tumor size, lymph node involvement, and metastasis in RCC." (PMID 40005423, 2025). "The INT2GRATE|VEF incorporates four key types of evidence to assess the clinical relevance of the VHL variants, including germline genetics, somatic genetics, clinical genetics, and tumor-derived data." (PMID 40647474, 2025). "Belzutifan, the first FDA-approved HIF-2α inhibitor, has shown remarkable efficacy in clinical trials, with a 60% reduction in tumor size and a 70% improvement in progression-free survival in patients with VHL-associated RCC." (PMID 40937003, 2025). "One of the earliest oncogenic events in the majority of ccRCC is the loss of function of tumor suppresor gene VHL." (PMID 40995093, 2025). "VHL-mutated tumor spheroids were significantly less infiltrated by NK cells compared with VHL-restored tumor spheroids." (PMID 40736709, 2025). "Our analyses suggest that different VHL variants have different organ-specific cellular and molecular functions that explain their different tumor propensity." (PMID 40202835, 2025). "About 30–40% of cases are the result of an underlying autosomal dominant familial disorder such as VHL (mutations in the VHL tumor suppressor gene), MEN2 (mutations in the RET proto-oncogene), and NF1 (mutations in the NF1 gene)." (PMID 40649858, 2025). "This study provides the first evidence of FSHR1 expression in tumor BV and cells, in VHL-associated tumors." (PMID 41024941, 2025). "Tumor development in this setting is caused by the loss of the remaining wild-type (WT) VHL allele as well as by ensuing mutations in other genes." (PMID 40178040, 2025). "Since NK cells have a prognostic value in ccRCC patients, it is important to understand how VHL mutations affect NK cell activity and anti-tumor immunity." (PMID 40736709, 2025). "The Von Hippel–Lindau (VHL) tumor suppressor gene, located on chromosome 3p25~26, encodes a multifunctional protein known as the pVHL, which exists in four isoforms: pVHL-213, pVHL-160, pVHL-172, and pVHL-X1." (PMID 41155273, 2025). "It has recently been demonstrated that loss of VHL can generate a hypoxic niche for tumor progenitor cell maintenance." (PMID 39920694, 2025). "Complete surgical resection is essential for long-term tumor control and favorable functional outcomes in both sporadic and VHL-associated sHBs." (PMID 39950840, 2025). "The patient's tumor demonstrated mutations in VHL, PBRM1, and SETD2, which are commonly associated with clear cell RCC and have significant implications for tumor behavior and therapy selection." (PMID 40600205, 2025). "Among them, mutation or methylation of the VHL gene (seen in 90% of sporadic ccRCC) promotes tumor progression through aberrant accumulation of hypoxia-inducible factor (HIF), which activates angiogenic and glycolytic pathways." (PMID 41584840, 2025). "In RCC, particularly in cells deficient in the VHL tumor suppressor gene, there is a pronounced reliance on glutamine for metabolic processes." (PMID 40677703, 2025). "As such, strategies to inhibit HIFα expression represent a valid approach to improve NK cell anti-tumor efficacy against VHL-mutated tumors." (PMID 40736709, 2025). "We noticed that there was no further reduction in tumor size at the higher dose of SKPin C1 (10 mg/kg vs 20 mg/kg), and vinorelbine showed much stronger antitumor effect than SKPin C1 on VHL-deficient RCC tumor xenograft." (PMID 40384876, 2025). "Among the tumors with somatic VHL alterations, ccRCC was the most frequent sporadic VHL-associated tumor." (PMID 40647474, 2025). "Together, these results show that restoration of VHL renders RCC tumor spheroids more susceptible to NK cell infiltration." (PMID 40736709, 2025).